MAPKAPK2 (MAPK activated protein kinase 2)
Description:
Stress-activated serine/threonine-protein kinase involved in cytokine production, endocytosis, reorganization of the cytoskeleton, cell migration, cell cycle control, chromatin remodeling, DNA damage response and transcriptional regulation. Following stress, it is phosphorylated and activated by MAP kinase p38-alpha/MAPK14, leading to phosphorylation of substrates. Phosphorylates serine in the peptide sequence, Hyd-X-R-X(2)-S, where Hyd is a large hydrophobic residue. Phosphorylates ALOX5, CDC25B, CDC25C, CEP131, ELAVL1, HNRNPA0, HSP27/HSPB1, KRT18, KRT20, LIMK1, LSP1, PABPC1, PARN, PDE4A, RCSD1, RPS6KA3, TAB3 and TTP/ZFP36. Phosphorylates HSF1; leading to the interaction with HSP90 proteins and inhibiting HSF1 homotrimerization, DNA-binding and transactivation activities. Mediates phosphorylation of HSP27/HSPB1 in response to stress, leading to the dissociation of HSP27/HSPB1 from large small heat-shock protein (sHsps) oligomers and impairment of their chaperone activities and ability to protect against oxidative stress effectively. Involved in inflammatory response by regulating tumor necrosis factor (TNF) and IL6 production post-transcriptionally: acts by phosphorylating AU-rich elements (AREs)-binding proteins ELAVL1, HNRNPA0, PABPC1 and TTP/ZFP36, leading to the regulation of the stability and translation of TNF and IL6 mRNAs. Phosphorylation of TTP/ZFP36, a major post-transcriptional regulator of TNF, promotes its binding to 14-3-3 proteins and reduces its ARE mRNA affinity, leading to inhibition of dependent degradation of ARE-containing transcripts. Phosphorylates CEP131 in response to cellular stress induced by ultraviolet irradiation which promotes binding of CEP131 to 14-3-3 proteins and inhibits formation of novel centriolar satellites. Also involved in late G2/M checkpoint following DNA damage through a process of post-transcriptional mRNA stabilization: following DNA damage, relocalizes from nucleus to cytoplasm and phosphorylates HNRNPA0 and PARN, leading to stabilization of GADD45A mRNA. Involved in toll-like receptor signaling pathway (TLR) in dendritic cells: required for acute TLR-induced macropinocytosis by phosphorylating and activating RPS6KA3.
Synonyms: MAPKAP-K2; MK-2; MK2
Tractability: Small molecule: a drug acting on it is in phase 1 trials; a structure with a bound ligand is known; a high-quality ligand is known; it has a high-quality binding pocket; it belongs to a druggable protein family. PROTAC: it is named in the literature on targeted protein degradation; UniProt records ubiquitination sites on it; ubiquitination databases record sites on it; its protein half-life has been measured; a small molecule that binds it is known.
Target class: CAMK protein kinase group; Kinase; Enzyme; CAMK protein kinase MAPKAPK subfamily; Protein Kinase; CAMK protein kinase MAPKAPK family
Chemical probes: CHEMBL1614995, PD081881, PD082139, PF3644022 (high quality)
Gene: Protein-coding gene on chromosome 1 (206,684,886 to 206,734,284, forward strand). Ensembl gene ENSG00000162889.
Subcellular location: Cytoplasm; Nucleus
Subcellular location (Human Protein Atlas): Nucleoplasm; Basal body; Centrosome
Pathways (Reactome):
Signal Transduction: CREB phosphorylation; Regulation of TNFR1 signaling; VEGFA-VEGFR2 Pathway; p38MAPK events
Cellular responses to stimuli: Oxidative Stress Induced Senescence; Regulation of HSF1-mediated heat shock response
Metabolism of RNA: Butyrate Response Factor 1 (BRF1) binds and destabilizes mRNA; Tristetraprolin (TTP, ZFP36) binds and destabilizes mRNA
Immune System: activated TAK1 mediates p38 MAPK activation
Metabolism: Synthesis of Leukotrienes (LT) and Eoxins (EX)
Gene Ontology:
Molecular function: protein binding; protein serine/threonine kinase activity; mitogen-activated protein kinase binding; protein kinase activity; ATP binding; protein serine kinase activity
Biological process: 3'-UTR-mediated mRNA stabilization; cellular response to vascular endothelial growth factor stimulus; DNA damage response; MAPK cascade; regulation of tumor necrosis factor production; response to cytokine; vascular endothelial growth factor receptor signaling pathway; inflammatory response; intracellular signal transduction; leukotriene metabolic process; macropinocytosis; regulation of cellular response to heat; regulation of interleukin-6 production; regulation of mRNA stability; regulation of tumor necrosis factor-mediated signaling pathway; response to lipopolysaccharide; toll-like receptor signaling pathway
Cellular component: cytoplasm; extracellular exosome; nucleoplasm; nucleus; cytosol
Genetic constraint (gnomAD): Loss-of-function variants: 8 observed, 47.68 expected, observed/expected ratio (o/e) 0.17, 90% interval 0.097 to 0.3. The upper end of that interval is the gene's LOEUF score, 0.3, which puts it in group 1 of 6, group 1 being the genes least tolerant of losing a copy. Missense variants: 288 observed, 464.97 expected, observed/expected ratio (o/e) 0.62, 90% interval 0.56 to 0.68. Synonymous variants: 182 observed, 175.81 expected, observed/expected ratio (o/e) 1.04, 90% interval 0.92 to 1.17.
Homologues: Orthologues: chimpanzee MAPKAPK2 (99% identical), pig MAPKAPK2 (96% identical), guinea pig MAPKAPK2 (90% identical), mouse Mapkapk2 (90% identical), rat Mapkapk2 (90% identical), macaque MAPKAPK2 (88% identical), rabbit MAPKAPK2 (79% identical), zebrafish mapkapk2a (78% identical), tropical clawed frog mapkapk2 (78% identical), zebrafish mapkapk2b (65% identical). Paralogues in human: MAPKAPK3 (65% identical), MAPKAPK5 (39% identical), CAMK4 (30% identical), MKNK1 (28% identical), MKNK2 (28% identical), DCX (13% identical).
Diseases named in the same sentence as MAPKAPK2 in open-access papers:
MAPKAPK2 is named in the same sentence as 72 diseases in open-access papers, as found by Europe PMC text mining. Sharing a sentence is not in itself a finding about the gene and the disease. The quoted sentences say what the papers report.
breast carcinoma (8 papers, 2010 to 2024). "Previous studies reported that MAPKAPK2 was involved in the chemotherapy or radiotherapy resistance in pancreatic cancer cells and breast cancer cells." (PMID 38322416, 2024). "MAPKAPK2 promotes the proliferation of head and neck squamous cell carcinoma, the metastasis of breast cancer, and the invasion of bladder cancer." (PMID 38322416, 2024). "MAPKAPK2 hotspots were shared across three entities, namely breast carcinoma (7 of 644 tumors), head and neck squamous cell carcinoma (3 of 56 tumors) and cervical squamous cell carcinoma (1 of 18 tumors)." (PMID 35013316, 2022). "For instance, copy number amplification of MAPKAPK2 is believed to elevate the prognostic risk of lung cancer patients, whereas copy number of MAPK kinase 3 is thought to increase breast cancer risk." (PMID 33585468, 2020). "Furthermore, MKK3 and the p38-activated kinase MAPKAPK2 (MK2) were shown to be involved in ARE-mediated mRNA stabilization in a Rac dependent manner in breast cancer cells." (PMID 21206905, 2010). "We find that Pim1, MAPKAPK2, and CK2 are kinases that are activated on the lung FDM, and were inhibited on the lung ECM alone, which would be good candidates to investigate when looking at breast cancer metastasis to the lungs." (PMID 34283050, 2021).
bladder cancer (6 papers, 2011 to 2024). "Recent data indicate that p38 MAPK-driven MAPKAPK2 regulates the invasion of bladder cancer by modulating MMP-2 and MMP-9 activities." (PMID 28678918, 2017). "A similar example is DUSP8, a gene whose promoter methylation predicts clinical outcome of ovarian cancer and MAPKAPK2, which is known to regulate invasion of bladder cancer." (PMID 24391728, 2013). "Studies have shown that bladder cancer invasion may be promoted by the p38 MAPK pathway through the regulation of the downstream MAPKAPK2 so as to regulate MMP-2 and MMP-9 activity." (PMID 29794990, 2018). "A recent report indicated that MAPKAPK2 could mediate p38 mitogen-activated protein kinase (MAPK) activation to drive invasion of bladder cancer by inducing the expression of MMP-2 and MMP-9." (PMID 22140479, 2011). "Hotspots in NTRK2 or MAPKAPK2 are not present in bladder carcinoma but in other entities (Head-SCC, Lung-AdenoCA and Uterus-AdenoCA)." (PMID 35013316, 2022).
colorectal cancer (6 papers, 2012 to 2024). A primary or metastatic malignant neoplasm that affects the colon or rectum. "However, the programmed cell death in human colorectal cancer cells is mediated by another signaling pathway—p38 MAPK/PUMA without the involvement of MAPKAPK-2 and c-Jun." (PMID 37373017, 2023).
glioblastoma (6 papers, 2016 to 2025). The most malignant astrocytic tumor (WHO grade IV). "We have demonstrated previously that acquired Hsp27 activation by p38 MAPK/MAPKAPK2/Hsp27 signaling cascade confers apoptosis-resistance to t-AUCB treatment in glioblastoma cells, although the cell proliferation inhibition and cell cycle G1 phase arrest induced by t-AUCB were significant." (PMID 27039073, 2016). "Further investigation into cellular function revealed that inhibiting MAPKAPK2 suppressed the proliferation and migration of glioblastoma multiforme (GBM) cells in vitro." (PMID 38322416, 2024).
lung carcinoma (6 papers, 2020 to 2024). "In addition, the efficiency of platinum-based chemotherapy in lung cancer mouse model was enhanced through phosphorylation of HNRNP A0 by MAPKAPK-2." (PMID 39366930, 2024). "METTL3 can promote the expression of multiple oncogenes such as BRD4, EGFR, TAZ, MAPKAPK2, and DNMT3A in human lung cancer cells." (PMID 34206803, 2021). "We have previously identified two gCNVs namely CNV-30450 in MAPKAPK2 and CNV-3956 in CHRNA7 as prognostic biomarkers for lung cancer survival based on candidate gene study design." (PMID 34178039, 2021). "Thus, interaction between DR and MAPKAPK2 may develop new strategies for lung cancer therapy." (PMID 32419823, 2020). "However, the results from an American research team indicated that METTL3 can increase the invasiveness of lung cancer cells by initiating the translation of oncogenes (EGFR, TAZ, and MAPKAPK2)." (PMID 32175271, 2020).
colon carcinoma (5 papers, 2016 to 2024). "MAPKAPK2 can regulate IL-1, IL-6, and chemokine expression in colitis-associated and spontaneous colon cancer models and promote the cancer progression." (PMID 38322416, 2024). "PRKRA rs10207436 was associated with reduced colon cancer risk (under the dominant model), while MAPKAPK2 rs4548444 was associated with increased risk (under the recessive model)." (PMID 27107574, 2016). "MAPKAPK2 is involved in many cellular processes, including stress and inflammatory response, gene regulation and cell proliferation, and nuclear export; as such, it is possible that the increased risk of colon cancer is associated with another biological process that MAPKAPK2 regulates." (PMID 27107574, 2016). "The chemokines induced by MAPKAPK2 signaling recruit macrophage influx to the colon cancer microenvironment and promotes colon cancer growth." (PMID 38322416, 2024). "As reported, MAPKAPK2 promotes colon tumor growth by regulating macrophage chemokine activity and recruitment." (PMID 38322416, 2024).
head and neck squamous cell carcinoma (5 papers, 2018 to 2024). A squamous cell carcinoma that arises from any of the following anatomic sites: lip and oral cavity, nasal cavity, paranasal sinuses, pharynx, larynx, and salivary glands. "In head and neck squamous cell carcinoma, inhibition of MAPKAPK2 reduced the production of inflammatory cytokines including IL-1α, IL-1β, and IL-6 induced by radiotherapy." (PMID 38322416, 2024). "MAPKAPK2 is also involved in chemotherapy (gemcitabine) resistance and radiation resistance in pancreatic cancer and head and neck squamous cell carcinoma." (PMID 38322416, 2024). "Mitogen-activated protein kinase-activated protein kinase-2 (MAPKAPK2) regulates transcript stability and exerts important effects in head and neck squamous cell carcinoma (HNSCC)." (PMID 34395233, 2021).
pancreatic cancer (5 papers, 2016 to 2024). "In present study, we first show that ethyl acetate extract of dark tea exhibits a significantly repressive effect on cell growth in pancreatic cancer cells, which is accompanied by enhanced MAPKAPK2 phosphorylation and decreased AKT phosphorylation." (PMID 31777585, 2019).
glioma (4 papers, 2012 to 2024). A benign or malignant brain and spinal cord tumor that arises from glial cells (astrocytes, oligodendrocytes, ependymal cells). "The present data provided evidence and clues to a better understanding of the glioma promoting role of MAPKAPK2 and the underlying mechanisms in glioma progression." (PMID 38322416, 2024). "Glioma patients in TCGA were divided into high- and low-risk groups according to the median value of MAPKAPK2 expression as the cutoff point." (PMID 38322416, 2024). "Our findings provide evidence of the clinical relevance of MAPKAPK2 in prognosis evaluation of glioma patients and highlight the underlying significance of MAPKAPK2 in glioma therapy." (PMID 38322416, 2024). "MAPKAPK2 was found to aggravate the proliferation and migration of glioma, and it was closely correlated with DNA damage repair and immune regulation in glioma tissue." (PMID 38322416, 2024). "In univariate Cox regression analyses, MAPKAPK2 was an independent prognostic factor in glioma in addition to WHO grades, 1p/19q codeletion status, and age." (PMID 38322416, 2024). "Further analyses of the relationship of MAPKAPK2 mRNA with the clinical pathological characters of glioma patients showed that MAPKAPK2 mRNA levels correlated with glioma grades, IDH genotype, 1p/19q co-deletion status, and the age of patients." (PMID 38322416, 2024). "Our data provide new insights into the role of MAPKAPK2 in the progression of glioma and present a promising strategy for glioma therapy involving MAPKAPK2 blockade." (PMID 38322416, 2024). "Here, our findings suggested that MAPKAPK2 mRNA and protein levels are both significantly elevated in glioma especially GBM and MAPKAPK2 is positively correlated with poor prognosis of glioma patients." (PMID 38322416, 2024). "GSEA enrichment analyses indicated that multiple pathways were closely correlated with MAPKAPK2 expression in glioma." (PMID 38322416, 2024). "In the present study, we show that MAPKAPK2 is aberrantly expressed in high-grade glioma tissues especially GBM." (PMID 38322416, 2024). "The results showed that MAPKAPK2 was overexpressed in glioma including GBM and LGG compared with the normal brain tissues." (PMID 38322416, 2024). "We also constructed a nomogram which included the MAPKAPK2 expression and other independent prognostic factors to predict the 1-, 3-, and 5-year survival probability of glioma patients." (PMID 38322416, 2024). "Consistent with the enriched function of MAPKAPK2 in immune regulation, MAPKAPK2 was correlated with immune cell infiltration in glioma tissues." (PMID 38322416, 2024). "Relationship of MAPKAPK2 protein levels with the clinicopathological characteristics of 93 glioma patients detected by IHC." (PMID 38322416, 2024). "Our data showed that MAPKAPK2 is mainly prevalent in macrophages and glioma cells and is positively correlated with the macrophage infiltration in glioma." (PMID 38322416, 2024). "Overall survival analyses of glioma patients from TCGA and CGGA were performed according to the median value of MAPKAPK2 as the cutoff point showed that high levels of MAPKAPK2 were correlated with poor prognosis of glioma patients." (PMID 38322416, 2024). "The MAPKAPK2 protein levels were significantly elevated in glioma tissues compared with the para-tumor tissues and were obviously higher in GBM compared with low-grade glioma." (PMID 38322416, 2024). "We found that MAPKAPK2 was positively correlated with neutrophils, eosinophils, helper T (Th) 2 cells, and Th17 cells in total glioma." (PMID 38322416, 2024). "MAPKAPK2 was not only aberrantly upregulated in glioma tissues but also correlated with poor clinical characteristics." (PMID 38322416, 2024). "Analyses of the ROC curve showed that the area under the ROC curve (AUC) was 0.946, which indicated the high prognostic value of MAPKAPK2 in glioma." (PMID 38322416, 2024).